MSH3 (mutS homolog 3)
Description:
Component of the post-replicative DNA mismatch repair system (MMR). When bound, the MutS beta heterodimer bends the DNA helix and shields approximately 20 base pairs. MutS beta recognizes large insertion-deletion loops (IDL) up to 13 nucleotides long. After mismatch binding, forms a ternary complex with the MutL alpha heterodimer, which is thought to be responsible for directing the downstream MMR events, including strand discrimination, excision, and resynthesis.
Synonyms: DUP; MRP1; FAP4
Tractability: Small molecule: a structure with a bound ligand is known. PROTAC: ubiquitination databases record sites on it; its protein half-life has been measured.
Safety:
Unwanted effects reported when the protein is acted on. In parentheses: how it was acted on, where the effect was seen, and who reports it.
drug toxicity (source: ClinPGx)
event-free survival (source: ClinPGx)
fatigue (source: ClinPGx)
leukopenia (source: ClinPGx)
overall survival (source: ClinPGx)
overall survival rates (source: ClinPGx)
Gene: Protein-coding gene on chromosome 5 (80,654,650 to 80,877,147, forward strand). Ensembl gene ENSG00000113318.
Subcellular location (Human Protein Atlas): Nuclear bodies
Pathways (Reactome):
Disease: Defective Mismatch Repair Associated With MSH3
Gene Ontology:
Molecular function: dinucleotide insertion or deletion binding; dinucleotide repeat insertion binding; enzyme binding; guanine/thymine mispair binding; mismatched DNA binding; oxidized purine DNA binding; protein binding; protein homodimerization activity; single guanine insertion binding; single-stranded DNA binding; ATP binding; ATP-dependent DNA damage sensor activity
Biological process: DNA repair; maintenance of DNA repeat elements; mismatch repair; negative regulation of DNA recombination; mitotic recombination; somatic recombination of immunoglobulin gene segments
Cellular component: membrane; MutSbeta complex; nucleus; nucleoplasm
Genetic constraint (gnomAD): Loss-of-function variants: 74 observed, 87.44 expected, observed/expected ratio (o/e) 0.85, 90% interval 0.7 to 1.03. The upper end of that interval is the gene's LOEUF score, 1.03, which puts it in group 4 of 6, group 1 being the genes least tolerant of losing a copy. Missense variants: 1,168 observed, 1,123.2 expected, observed/expected ratio (o/e) 1.04, 90% interval 0.99 to 1.09. Synonymous variants: 410 observed, 412.09 expected, observed/expected ratio (o/e) 0.99, 90% interval 0.92 to 1.08.
Gene-disease validity (ClinGen):
ClinGen rates the evidence that MSH3 causes each of these diseases.
familial adenomatous polyposis 4 (autosomal recessive): Definitive. An autosomal recessive tumor predisposition syndrome characterized by the development of multiple colonic adenomas in adulthood, often with progression to colorectal cancer.
Lynch syndrome (autosomal dominant): Disputed. An autosomal dominant hereditary neoplastic syndrome characterized by the development of colorectal carcinoma and a high risk of developing endometrial carcinoma, gastric carcinoma, ovarian carcinoma, renal pelvis carcinoma, and small intestinal carcinoma.
Homologues: Orthologues: chimpanzee MSH3 (99% identical), macaque MSH3 (95% identical), pig MSH3 (86% identical), dog MSH3 (85% identical), mouse Msh3 (78% identical), rat Msh3 (78% identical), rabbit MSH3 (73% identical), guinea pig MSH3 (72% identical), tropical clawed frog msh3 (57% identical), zebrafish msh3 (50% identical). Paralogues in human: MSH6 (24% identical), MSH4 (18% identical), MSH5 (16% identical).
Diseases named in the same sentence as MSH3 in open-access papers:
MSH3 is named in the same sentence as 114 diseases in open-access papers, as found by Europe PMC text mining. Sharing a sentence is not in itself a finding about the gene and the disease. The quoted sentences say what the papers report.
colorectal cancer (43 papers, 2010 to 2026). A primary or metastatic malignant neoplasm that affects the colon or rectum. "Loss of MSH3 function is an acquired somatic defect seen in 50% of colorectal cancers and triggered by proinflammatory interleukin-6 signaling, causing a reversible nuclear-to-cytoplasmic shift of the protein." (PMID 40989818, 2025). "Loss of MSH3 function is observed in 50% of colorectal cancers as determined by its failed MMR function (EMAST), but also the accumulation of loss of heterozygosity events potentially driven by failed DSB repair at targeted sites in the genome." (PMID 40989818, 2025). "Here, we describe the 9th case of an individual with germline compound heterozygous MSH3 variants with early-onset colorectal cancer (CRC)." (PMID 38243056, 2024). "Mismatch repair-deficient colorectal cancer clones adapt their mutation landscape by toggling homopolymer sequences in MutS homolog 3 (MSH3) and MutS homolog 6 (MSH6)." (PMID 38956208, 2024). "Another MSH3 functional polymorphism, +3133A/G (rs26279), associated with a higher predisposition to colorectal cancer, near the ATP binding site within the ATPase domain, has also been identified." (PMID 39199686, 2024). "Biallelic pathogenic variants in MSH3 gene are associated with the development of multiple colonic adenomas in adulthood, which often progress to colorectal cancer." (PMID 37895483, 2023). "Next-generation sequencing and copy number variation analysis of a panel of genes associated with colorectal cancer and polyposis revealed compound heterozygous germline pathogenic variants in the MSH3 gene." (PMID 35675019, 2023). "The variants described in ATF7IP and MSH3 are related to prostate and colorectal cancer, respectively." (PMID 35563252, 2022). "MSH3 gene or protein deficiency or loss-of-function in colorectal cancer can cause a DNA mismatch repair defect known as “elevated microsatellite alterations at selected tetranucleotide repeats” (EMAST)." (PMID 34298744, 2021). "This secondary mutation of MSH3 happens in about one-third to one-half of sporadic MSI-H colorectal cancers and perhaps less often among Lynch cancers." (PMID 25836926, 2015). "One report indicates that MSH-H colorectal cancers with secondary MSH3 mutation demonstrates decreased wall invasiveness and aneuploidy histologically, but this has not been confirmed in any other study." (PMID 25836926, 2015). "At present, it is not known if secondary mutations within any target genes as a result of MSH3 dysfunction change the behavior of colorectal cancer." (PMID 25836926, 2015). "MSH3 is a DNA mismatch repair (MMR) gene that undergoes frequent somatic mutation in colorectal cancers (CRCs) with MMR deficiency." (PMID 23724141, 2013). "Elevated microsatellite instability at selected tetranucleotide repeats (EMAST) is a genetic signature in certain cases of sporadic colorectal cancer and has been linked to MSH3-deficiency." (PMID 23209772, 2012). "Pathogenic variants of MSH3 can increase mutational load within colorectal cells, which may drive initiation and progression of colorectal cancer (CRC)." (PMID 42253507, 2026). "MSH3 is associated with the development of various cancers, and some studies have shown that MSH3 is associated with the development of primary nasopharyngeal, prostate cancer, esophageal cancer, colorectal cancer, breast cancer, while studies on renal cell carcinoma are rare." (PMID 37426643, 2023). "Therefore, there is an obligatory overlap of tetranucleotide repeat instability and MSI-H colorectal cancers, but MSH3-related EMAST is linked with the MSI-L phenotype." (PMID 34298744, 2021).
colorectal cancer (continued). "Furthermore, the mutational frequency in MSI-H colorectal cancer is 20 to 39% for MSH3 and 30 to 40% for MSH6." (PMID 20979647, 2010). "Unlike MSI-H colorectal cancers in which hypermethylation of MLH1 drives multiple target gene mutations, to date there has been little evidence for mutation of specific target genes that might drive or alter the pathogenesis of colorectal cancer with loss of MSH3 function." (PMID 25836926, 2015). "Patients with colorectal cancer had large frequency of variants in genes APC (50.2%), KRAS (23.2%), BRAF (14.6%), RNF43 (12.3%), and MSH3 (11.3%)." (PMID 39277826, 2024). "Another downregulated gene, MSH3, takes part in pathways of platinum drug resistance, mismatch repair, and colorectal cancer, and it is related to colorectal cancer, endometrial cancer, and familial adenomatous polyposis." (PMID 37546388, 2023). "Some colorectal cancers are signified by MMR deficiencies, such as LOF of MSH3 or MSH6, creating a high number of deletions in repetitive DNA." (PMID 36883553, 2023). "We used the colorectal cancer line HCT116, which is mutated in both MSH3 and MLH1, alongside the MMR-proficient HCT116 cell line complemented with chromosomes 5 and 3 that house the wild-type copies of the two genes, respectively 28,29." (PMID 35140211, 2022). "This is essentially in line with reports of reduced nuclear MSH3 expression in EMAST‐positive colorectal cancer." (PMID 35099128, 2022). "Tetranucleotide microsatellite instability, which is caused by MSH3 mismatch repair gene/protein loss-of-function, shares a molecular basis with “low microsatellite instability” (MSI-L) in colorectal cancer." (PMID 34298744, 2021). "To evaluate MSH3 gene alteration and expression in a larger cohort, we analysed publicly available data from ~3000 colorectal cancer patients using cBioPortal for Cancer Genomics." (PMID 34298744, 2021). "MSH3 copy number alterations occur in another ~32% of colorectal cancers; one copy is deleted in 24% (128/524), both copies in 0.2% (1/524) and copy gain is found in 8% (41/524)." (PMID 34298744, 2021). "MSI-H is rare in colorectal cancers with MSH3 copy number alterations but common in diploid cancers." (PMID 34298744, 2021). "MSH3-related EMAST is emerging as a biomarker of poor prognosis in colorectal cancer and needs to be clearly differentiated from MSI-H." (PMID 34298744, 2021). "Our previous study regarding mutations in DNA-repair-associated genes in colorectal cancer demonstrated that EMAST+/MSI-H tumors had a higher frequency of MLH1, MSH3, MSH6, PMS2, and EXO1 genetic mutations than the other three colorectal cancer subtypes." (PMID 32120855, 2020). "Both papers data on tetranucleotide frameshifts from MSH3 dysfunction contrast the near uniform observation that mono- or dinucleotide microsatellite sequences in human colorectal cancer only contract in size." (PMID 25836926, 2015). "Further exploration into the inciting and driving events that modify patient outcome as a result of EMAST and MSH3 dysfunction in colorectal cancers should yield potential approaches for primary or secondary intervention for patients." (PMID 25836926, 2015). "TGFBR2, MSH3 and MSH6 microsatellite sequences present high mutational rates in right MSI-H colorectal cancer, demonstrating that alterations in these genes are important for the development of MSI neoplasias." (PMID 20979647, 2010).
colorectal cancer (continued). "It has been shown in human colorectal cancer cell lines, specifically in HT29 carrying the full-length (FL) allele and SW480 harboring the deletion (Δ) allele, that treatment with IL-6 induces the relocation of the MSH3 protein." (PMID 39199686, 2024). "Dense immune cell infiltration within these tumors combined with the finding of heterogeneous MSH3 expression in EMAST colorectal cancers indicated that inflammation might have an impact on the functionality of MSH3." (PMID 37510378, 2023). "MSH3 is closely related to the occurrence and development of colorectal cancer." (PMID 36478716, 2022). "MSH3 alterations are associated with elevated microsatellite alterations at selected tetranucleotide repeats (EMAST), the most common DNA mismatch repair defect in colorectal cancers, observed in approximately 60% of analyzed cancers." (PMID 33923292, 2021). "Loss of MSH3 can occur with mutation in MSI-H colorectal cancers, but it is not clear if the additional loss of MSH3 adds further phenotype to the cancer cells." (PMID 25836926, 2015). "The congruence of inflammation and heterogeneous expression of MSH3 in EMAST colorectal cancers suggested that they might be related to each other." (PMID 25836926, 2015). "Although the EMAST biomarker is inclusive among MSI-H colorectal cancers due to the complete absence DNA mismatch repair, it, as a stand-alone biomarker with isolated MSH3 dysfunction, shows a different clinicopathogenic portfolio when compared to MSI-H cancers." (PMID 25836926, 2015). "Additionally, MSH3 expression in EMAST colorectal cancers became heterogeneous among cells within the tumor, and the nuclei of the cancer cells themselves became heterogeneous for MSH3 expression." (PMID 25836926, 2015). "Furthermore, down-regulation of MSH3 was found to induce a MSI-L phenotype in sporadic colorectal cancer (reviewed by Boland and Goel, 2010)." (PMID 22623965, 2012). "In colorectal cancer, mutations have been found in a number of genes with key cellular roles, such as growth factor receptors (TGFBR2 and IGF2R), genes involved in apoptosis (BAX), as well as genes relevant for DNA repair (MSH3, MSH6)." (PMID 20979647, 2010). "All participating siblings aged ≥ 55 without the compound heterozygous MSH3 variants participated in the Dutch national colorectal cancer screening program (biannual faecal immunochemical testing (FIT) between the ages of 55 and 75), and have all received negative FIT-results so far." (PMID 35675019, 2023). "Moreover, the recent advances in molecular techniques, in particular Next-Generation Sequencing, have led to the identification of many new genes involved in the predisposition to colorectal cancers, such as RPS20, POLE, POLD1, AXIN2, NTHL1, MSH3, RNF43 and GREM1." (PMID 36768460, 2023). "In the HMF colorectal cancers, we discovered eight predictive gene deficiency models (MSH3, SMC2, SMC6, BMPR2, CLASP2, SRCAP, UBR5, and UVRAG) of monoallelic LOF with PR-AUC-E ranging from 0.21 (CLASP2) to 0.62 (MSH3) (AUROC ranging from 0.68 for SRCAP deficiency to 0.94 for MSH3 deficiency)." (PMID 36883553, 2023). "This patient did not present with polyposis and suggests that there may be additional cases with biallelic pathogenic MSH3 germline variants without severe polyposis as a clinical presentation, and MSH3 analysis should be considered in all individuals with early-onset colorectal cancer." (PMID 38243056, 2024). "The genes MSH3 and MLH3 are known cancer genes originally identified in colorectal cancer." (PMID 39272813, 2024). "This led to a subsequent perception that MSH3 is not so important in tumorigenesis, at least in the context of colorectal cancer, in which it was mostly investigated." (PMID 37510378, 2023). "Defective MSH3 function or loss of gene expression causes EMAST and can occur through multiple mechanisms, but the role of MSH3 gene silencing has not yet been investigated in colorectal cancer." (PMID 34298744, 2021).
colorectal cancer (continued). "After ruling out TNFα, IL1β, IFNα and IFNγ, the authors show that IL6 induces the MSH3 nuclear-to-cytosol compartmental shift, and is coincident with the generation of oxidative stress within colorectal cancer cells and non-transformed colon cells." (PMID 25836926, 2015). "Among colorectal cancers, EMAST shows a strong correlation with the level of chronic inflammation in the tumor, in addition to its correlation with heterogeneous and decreased MSH3 expression." (PMID 25836926, 2015). "Here, we also show that the MSH3 gene promoter is not methylated in colorectal cancer." (PMID 34298744, 2021). "Furthermore, our data suggest that down-regulation of MSH3 mRNA does not correlate with the presence of 1–2 EMAST-positive markers in colorectal cancer." (PMID 34298744, 2021). "Hypoxia and low pH may be other factors within colorectal cancers or non-cancer inflamed tissues to reduce MSH3 expression." (PMID 25836926, 2015). "The MSH3 gene is silenced through promoter methylation in gastric cancer, but the relevance of promoter methylation for the generation of EMAST has not been reported yet in colorectal cancer." (PMID 34298744, 2021).